COL15A1 (collagen type XV alpha 1 chain)
Description:
Structural protein that stabilizes microvessels and muscle cells, both in heart and in skeletal muscle. Restin potently inhibits angiogenesis.
Tractability: Antibody: UniProt places it where antibodies can reach, with high confidence; its Gene Ontology location is reachable by antibodies, with high confidence; UniProt predicts a signal peptide or a membrane-spanning region. Other modalities: an approved drug acts on it.
Gene: Protein-coding gene on chromosome 9 (98,942,680 to 99,070,797, forward strand). Ensembl gene ENSG00000204291.
Subcellular location: Secreted, extracellular space, extracellular matrix; Secreted
Subcellular location (Human Protein Atlas): Endoplasmic reticulum; Predicted to be secreted
Pathways (Reactome):
Extracellular matrix organization: Assembly of collagen fibrils and other multimeric structures; Collagen biosynthesis and modifying enzymes; Collagen chain trimerization; Collagen degradation
Gene Ontology:
Molecular function: extracellular matrix structural constituent conferring tensile strength
Biological process: extracellular matrix organization; signal transduction
Cellular component: endoplasmic reticulum; extracellular exosome; extracellular matrix; extracellular region; basement membrane; collagen type XV trimer; endoplasmic reticulum lumen; membrane; collagen trimer
Genetic constraint (gnomAD): Loss-of-function variants: 83 observed, 130.59 expected, observed/expected ratio (o/e) 0.64, 90% interval 0.53 to 0.76. The upper end of that interval is the gene's LOEUF score, 0.76, which puts it in group 3 of 6, group 1 being the genes least tolerant of losing a copy. Missense variants: 1,419 observed, 1,530.8 expected, observed/expected ratio (o/e) 0.93, 90% interval 0.89 to 0.97. Synonymous variants: 566 observed, 587.36 expected, observed/expected ratio (o/e) 0.96, 90% interval 0.9 to 1.03.
Homologues: Orthologues: chimpanzee COL15A1 (99% identical), pig COL15A1 (81% identical), dog COL15A1 (81% identical), rabbit COL15A1 (78% identical), mouse Col15a1 (74% identical), rat Col15a1 (73% identical), zebrafish col16a1 (19% identical), zebrafish col19a1 (13% identical). Paralogues in human: COL5A1 (26% identical), COL11A2 (25% identical), COL11A1 (25% identical), COL4A5 (25% identical), COL5A3 (24% identical), COL4A1 (23% identical), COL4A3 (23% identical), COL4A2 (23% identical), COL4A6 (22% identical), COL2A1 (21% identical), COL4A4 (21% identical), COL1A1 (21% identical), and 25 more.
Diseases named in the same sentence as COL15A1 in open-access papers:
COL15A1 is named in the same sentence as 76 diseases in open-access papers, as found by Europe PMC text mining. Sharing a sentence is not in itself a finding about the gene and the disease. The quoted sentences say what the papers report.
breast carcinoma (6 papers, 2021 to 2024). "Another 9 types of malignancies, including breast cancer and colorectal cancer, have high levels of COL15A1 expression that are associated with high MSI levels." (PMID 39088036, 2024). "In addition, COL3A1, COL4A1, COL5A1, and COL15A1 are associated with immune infiltration in head and neck squamous cell carcinoma, breast cancer, mesothelioma, and other tumors." (PMID 34691289, 2021). "In a transgenic MMTV-PyMT mouse mammary carcinoma model, inactivation of COL15A1 modulated the tumor extracellular matrix and increased mammary tumor growth." (PMID 38371376, 2024). "The findings depicted that the expression of COL15A1 has an association with the tumor microenvironment (TME) in 15 types of cancers, including breast cancer, liver cancer, and pancreatic carcinoma." (PMID 39088036, 2024). "Expression levels of the ECM structural proteins Col5A1 and Col15A1 significantly decreased while Col14A1 significantly increased in lung fibroblasts exposed to factors from metastatic breast cancer cells as compared to controls." (PMID 37903851, 2023). "Our data of increased mammary tumour growth in the PyMT;Col15a1−/− mice and the previous data on diminished ColXV expression in human breast cancer raise the question of the relation between ColXV levels and patient survival." (PMID 34576139, 2021). "We found increased mammary tumour growth in the PyMT;Col15a1−/− mice in comparison with control PyMT mice almost through the follow-up period, except for in the latest examined time points, when the tumour burden was the same in both experimental groups." (PMID 34576139, 2021). "We show here for the first time that the inactivation of Col15a1 in mice leads to changes in the fibrillar tumour matrix and to increased mammary tumour growth." (PMID 34576139, 2021). "However, based on the analysis of microvessel density and vascular area in the PyMT;Col15a1−/− mammary tumours, we postulated that, relative to controls, the knockout tumours have fewer vessels but are larger in size." (PMID 34576139, 2021). "It has been reported that deletion of COL15A1 modulates the tumor ECM and leads to increased tumor growth in the mouse mammary carcinoma model." (PMID 37089260, 2023).
atherosclerosis (3 papers, 2020 to 2022). A disease characterized by the build-up of fatty material and calcium deposition in the arterial wall resulting in partial or complete occlusion of the arterial lumen. "Genetic analyses have suggested that COL15A1 is associated with atherosclerosis in aged individuals." (PMID 33086603, 2020). "In 2013, a single nucleotide polymorphism within COL15A1 has been reported to correlate with atherosclerosis in aged individuals." (PMID 33543021, 2020). "COL15A1 is a novel atherosclerosis gene that is involved in vascular smooth muscle cell phenotype, which is regulated by epigenetic state in passaged cells and located in atherosclerotic tissue." (PMID 35747248, 2022). "In the context of atherosclerosis, the expression of Col15a1 in SMCs is interesting because COL15A1 affects both the proliferative and migratory phenotypes of this cell type." (PMID 33086603, 2020). "COL15A1 was also found to be upregulated with age in human and mouse atherosclerosis resulting in abnormal protein deposits in the affected blood vessels." (PMID 33543021, 2020). "Surprisingly, Col15a1 KO mice that have been fed to develop atherosclerosis, failed to form advanced lesions and, on the contrary, presented lesion size reduction by 78%." (PMID 33543021, 2020).
cardiomyopathy (3 papers, 2020 to 2025). A disease of the heart muscle or myocardium proper. "Mice lacking COL15A1 and COL18A1 genes present impaired heart function phenotypes; specifically, Col15a1(-/-) knockout leads to a complex cardiac phenotype and predisposes mice to cardiomyopathy." (PMID 36292100, 2022). "Col15a1‐deficient mice exhibit non‐proto‐fibrillar protein deposits in the cardiac myocardium interstitium, along with an abnormal increase in the Col1a1/Col3a1 ratio, heightened myocardial stiffness, reduced elasticity, and decreased myocardial compliance, ultimately leading to cardiomyopathy." (PMID 39592912, 2025). "The cardiomyopathy developed by the Col15a1−/− mice is essentially characterized by structural alterations of the myocardium and cardiac capillaries." (PMID 33543021, 2020). "Detailed analyses of the Col15a1−/− mouse phenotype revealed that the mutant mice also suffered from a mild but complex cardiomyopathy showing progressive symptoms and signs." (PMID 33543021, 2020).
head and neck squamous cell carcinoma (3 papers, 2021 to 2025). A squamous cell carcinoma that arises from any of the following anatomic sites: lip and oral cavity, nasal cavity, paranasal sinuses, pharynx, larynx, and salivary glands. "Recent research has also highlighted the prevalence of COL15A1+ myCAFs in head and neck squamous cell carcinoma (HNSCC) patients, particularly in the peritumoral tissues across various cancers, where they are associated with tissue repair and regeneration." (PMID 40107247, 2025).
hepatocellular carcinoma (3 papers, 2019 to 2024). A malignant tumor that arises from hepatocytes. "CCK8 assay was employed to observe the effect of COL15A1 on the proliferative viability of hepatocellular carcinoma cells, and the results showed that high expression of COL15A1 significantly inhibited the proliferation of tumor cells." (PMID 39088036, 2024). "Subsequently, we overexpressed COL15A1 in hepatocellular carcinoma cells and detected the expression level of COL15A1 in the tumor cells by qRT-PCR and Western blot." (PMID 39088036, 2024). "To investigate the effect of COL15A1 on tumor progression, we selected hepatocellular carcinoma cells to verify its effect on tumor cell progression." (PMID 39088036, 2024). "With qRT-PCR and Western blot we found that the expression of COL15A1 in hepatocellular carcinoma tissues was lower than that in normal liver tissues, and we selected types of hepatocellular carcinoma cells (HepG2 and LM3) for subsequent work." (PMID 39088036, 2024). "Meanwhile, Transwell assay showed that overexpression of COL15A1 inhibited the migration and invasion of hepatocellular carcinoma cells." (PMID 39088036, 2024). "The overall association scores for hepatocellular carcinoma were 0.210 for HOXD9, 0.174 for NDST3, 0.111 for PZP, 0.106 for E2F8, 0.061 for ADRA2B, and 0.029 for COL15A1." (PMID 31754347, 2019). "However, the COL15A1 expression has been reported to be substantially greater in hepatocellular carcinoma compared to normal liver tissue, thus leading to poor prognosis." (PMID 39088036, 2024). "Similarly, the inhibition of hepatocellular carcinoma cell migration by high expression of COL15A1 compared to the control group could be observed in the wound healing assay." (PMID 39088036, 2024).
idiopathic pulmonary fibrosis (3 papers, 2021 to 2025). Idiopathic pulmonary fibrosis (IPF) is a nonneoplastic pulmonary disease that is characterized by the formation of scar tissue within the lungs in the absence of any known cause. "‘COL23A1+ adventitial fibroblasts’ shared key markers (COL15A1, ENTPD1, PLCL1) with peribronchial fibroblasts, a subpopulation specifically localized around the airway epithelium, which is enriched in idiopathic pulmonary fibrosis and may be implicated as a key cell type in lung disease." (PMID 40114924, 2025).
Obesity (3 papers, 2019 to 2025). Accumulation of substantial excess body fat. "Consistent with the functional enrichment analyses, we identified hub genes related to blood vessel morphogenesis in the darkred module: TBXA2R, FZD4, COL15A1, and TBX2 were positively associated with maternal BMI and/or obesity and with birth weight." (PMID 31110514, 2019).
ovarian carcinoma (3 papers, 2024 to 2025). A malignant neoplasm originating from the surface ovarian epithelium. "We identified an unreported genetic variant, rs7027650, that was significantly associated with ovarian cancer risk and significantly correlated with the expression of COL15A1 in eQTL analysis." (PMID 38371376, 2024). "We also demonstrated that rs7027650 may regulate COL15A1 gene expression, offering suggestions for further functional studies to clarify the underlying biological mechanism in ovarian cancer etiology." (PMID 38371376, 2024). "Collectively, these molecular analyses and experiments suggested that SNP rs7027650 may be a functional variant, potentially affecting COL15A1 transcription regulation and may affect ovarian cancer carcinogenesis." (PMID 38371376, 2024). "Apparently, the role of COL15A1 in cancer seems to be a complex problem; it exhibited elevated levels of expression in various chemoresistant ovarian cancer cell lines, but its inhibition promoted an aggressive phenotype in the hepatoblastoma cell line." (PMID 39457549, 2024). "RNA sequencing of ovarian carcinoma-TA-MSCs identifies a distinct predictive algorithm comprising six genes: Annexin A8-like protein 2 (ANXA8L2), Collagen Type XV Alpha 1 Chain (COL15A1), Cytokine Receptor Like Factor 1 (CRLF1), GATA Binding Protein 4 (GATA4), Iroquois Homeobox 2 (IRX2), and TGF‐β2." (PMID 40676710, 2025).
breast tumor (2 papers, 2023 to 2025). "Studies have shown that Col15a1 inactivation in mice alters the fibrotic tumor microenvironment and promotes breast tumor progression." (PMID 40176796, 2025).
gastric cancer (2 papers, 2022 to 2024). A primary or metastatic malignant neoplasm involving the stomach. "In previous studies, high expression of COL15A1 promoted gastric cancer progression at the protein level by affecting lipid metabolism, this is in good agreement with the findings of our research." (PMID 39088036, 2024). "Another cell compendium of cross-tissue fibroblast, described steady-state fibroblast, positive for PI16 and COL15A1, which were strikingly similar to resting fibroblast in our gastric cancer data." (PMID 36550535, 2022).
glaucoma (2 papers, 2015 to 2025). Increased pressure in the eyeball due to obstruction of the outflow of aqueous humor. "Notably, emerging molecular epidemiology evidence demonstrates that polymorphic variants in COL15A1 and COL18A1 genes substantially modulate the temporal onset and clinical trajectory of primary open-angle glaucoma (POAG)." (PMID 40176796, 2025).
liver cancer (2 papers, 2023 to 2024). An epithelial or non-epithelial malignant neoplasm that arises from the liver. "Several reports of COL15A1 being related to the occurrence of liver cancer, ovarian cancer, lung cancer, and rectal cancer have been documented in the literature." (PMID 39088036, 2024). "PILC-BSCSO identifies a subset of five marker genes, including prognostic biomarkers HMMR, CHST4, and COL15A1, that have excellent predictive potential for liver cancer using TCGA data." (PMID 37892853, 2023).
liver fibrosis (2 papers, 2021 to 2025). "Furthermore, we demonstrated that single cell sequencing helps identifying novel, cell-specific markers such as COL15A1, ALOX5AP, and LAPTM5 that could further improve our understanding of liver fibrosis." (PMID 33922101, 2021).
lung adenocarcinoma (2 papers, 2020 to 2024). A carcinoma that arises from the lung and is characterized by the presence of malignant glandular epithelial cells. "Six genes (COL3A1, COL1A2, OGN, COL15A1, ASPN, and MXRA5) and three miRNAs (hsa-miR-29c-3p, hsa-let-7c-5p, and hsa-miR-29b-3p) were related to the survival time of lung adenocarcinoma (LUAD)." (PMID 32300359, 2020).
lung carcinoma (2 papers, 2022 to 2026). "Col4a3 expression is associated with the poor prognosis of lung cancer patients after receiving chemotherapy, and Col8a1, Col5a3, and Col15a1 are involved in tumor growth and development." (PMID 35565312, 2022).
mesothelioma (2 papers, 2021 to 2024). A usually malignant and aggressive neoplasm of the mesothelium which is often associated with exposure to asbestos. "Also, the prognosis of mesothelioma is associated with COL3A1, COL4A1, and COL15A1." (PMID 34691289, 2021).
sarcoma (2 papers, 2021 to 2024). A usually aggressive malignant neoplasm of the soft tissue or bone. "None of the tested cancer cell lines, namely T241 sarcoma, LLC1 Lewis lung carcinoma or B16F10 melanoma, showed differences in primary tumour growth rates between Col15a1+/+ and Col15a1−/− mice when injected subcutaneously." (PMID 34576139, 2021).
acute myeloid leukemia (1 paper, 2024). Acute myeloid leukemia (AML) is a group of neoplasms arising from precursor cells committed to the myeloid cell-line differentiation. "All malignancies expressed COL15A1, and the highest levels of COL15A1 expression were found in PAAD while the lowest levels were found in acute myeloid leukemia (LAML)." (PMID 39088036, 2024).
acute myocardial infarction (1 paper, 2026). Necrosis of the myocardium, as a result of interruption of the blood supply to the area. "Numerical data of echocardiographic measurements and heart and body weights for wild‐type (WT) and Col15a1−/− mice before subjected to acute myocardial infarction (AMI), as well as 1 and 5 weeks after AMI." (PMID 40832756, 2026). "Fold changes in the qPCR analysis between the wild‐type (WT) and Col15a1−/− remote left ventricles after acute myocardial infarction (AMI) (n = 5 per genotype)." (PMID 40832756, 2026).
asthma (1 paper, 2020). "Five novel hub DEGs (i.e., JAM2, SIGLECP3, C14orf186, COL15A1, and GIMAP6) were identified in asthma-IPF among ten hub DEGs." (PMID 31952466, 2020). "In addition, other identified genes were LRRC48 and CETN2 in asthma-COPD, COL15A1, GIMAP6, and JAM2 in asthma-IPF, along with LMO7, TSPAN13, LAMA3, and ANXA3 in COPD-IPF." (PMID 31952466, 2020). "These genes included RBM42, STX5, and TRIM41 in asthma, CYP27A1, GM2A, LGALS9, SPI1, and NLRC4 in COPD, ATF3, PPP1R15A, ZFP36, SOCS3, NAMPT, and GADD45B in IPF, LRRC48 and CETN2 in asthma-COPD, COL15A1, GIMAP6, and JAM2 in asthma-IPF and LMO7, TSPAN13, LAMA3, and ANXA3 in COPD-IPF." (PMID 31952466, 2020). "Accordingly, COL15A1, GIMAP6, and JAM2 may present a novel therapeutic strategy for the asthma-IPF." (PMID 31952466, 2020).
cystic fibrosis (1 paper, 2020). Autosomal recessive disorder caused by pathogenic variants in the CFTR gene (cystic fibrosis transmembrane conductance regulator), which encodes a chloride and bicarbonate channel expressed in epithelial cells, and follow the diagnosis criteria. "In addition, COL15A1 is a potential marker for portal fibroblasts with a significant role in biliary fibrosis, while CFTR is a well-known gene for cystic fibrosis, a disease with similar symptoms as BA." (PMID 32848883, 2020).
diffuse large B-cell lymphoma (1 paper, 2024). "A statistically significant positive association is available between the MMR gene expression level and COL15A1 expression levels in various cancers, such as CHOL and Lymphoid Neoplasm Diffuse Large B-cell Lymphoma (DLBC)." (PMID 39088036, 2024).
fibrosarcoma (1 paper, 2021). A malignant mesenchymal fibroblastic neoplasm affecting the soft tissue and bone. "Thus, subcutaneous fibrosarcomas were induced in the Col15a1+/+ control and Col15a1−/− knockout mice, both in the C57BL/6JOlaHsd background, with a 3-methylchlolantrene (MCA) treatment." (PMID 34576139, 2021). "We also show that, in robust tumour cell transplantation models or in a chemical-induced fibrosarcoma model, the inactivation of Col15a1 does not affect tumour growth or angiogenesis." (PMID 34576139, 2021).
glioma (1 paper, 2024). A benign or malignant brain and spinal cord tumor that arises from glial cells (astrocytes, oligodendrocytes, ependymal cells). "Thus, we concluded that the GBM hsa_circ_0001081/miR-26b-5p/COL15A1-affected subcluster of collagen-enriched genes can help distinguish the mesenchymal glioma molecular subtype from other molecular subtypes." (PMID 39457549, 2024).
hepatic (1 paper, 2025). "Differential regulation of the hepatic stellate cell activation and hepatic fibrosis pathways was largely driven by upregulation of 17 collagen isoforms, including COL12A1, COL15A1, COL16A1, and COL1A1." (PMID 40040391, 2025).
infarction (1 paper, 2026). A localised pathological necrosis of tissue resulting from obstruction of the blood supply usually by a thrombus, an embolus, or vascular torsion. "Moreover, infarction promoted more strongly heart stiffness in Col15a1−/− mice than in the WT littermates when compared with the baseline values (23.2 kPa in WT AMI; P < 0.05 and 35.1 kPa in Col15a1−/− AMI; P < 0.0001)." (PMID 40832756, 2026).
kidney damage (1 paper, 2023). "The BLNK, MS4A4A, and COL15A1 were all negatively correlated with eGFR, indicating that these genes may aggravate kidney damage in patients with DN." (PMID 36765416, 2023).
Myocardial fibrosis (1 paper, 2025). "Thus, our findings suggest that Fmod may promote DCM‐related myocardial fibrosis by regulating Col15a1 expression." (PMID 39592912, 2025).
myopia (1 paper, 2022). "Taken together, scleral Col1a1, Col4a3, Col8a2, Col11a2, and Col15a1 expression were regulated through ER stress during the myopia progression." (PMID 36216837, 2022).